PRC1 (protein regulator of cytokinesis 1)
Diseases named in the same sentence as PRC1 in open-access papers (continued):
Sharing a sentence is not in itself a finding about the gene and the disease.
cancer (continued). "Next, we investigated whether the effect of CDK16 on different types of cancer cell lines was also mediated via PRC1 phosphorylation." (PMID 30992425, 2019). "Previous studies have provided evidence that PRC1 is involved in different types of cancer." (PMID 30881920, 2019). "Therefore, regulation of CAF1 levels by Src, which in turn affects PRC1 expression levels, further supports the idea of cancer phenotypes resulting from a form of ectopic de-differentiation." (PMID 29904729, 2018). "We found that PRC1 genes were amplified in multiple cancer types." (PMID 30139998, 2018). "Kinesin and PRC1 expression was detected in all cancer cell lines." (PMID 29435157, 2018). "Previous studies have shown that some cancer cells are highly dependent on PRC1 for proliferation." (PMID 29752448, 2018). "Nonetheless, despite great efforts to understand the epigenetic mechanisms that contribute to human maladies, a comprehensive analysis of genomic alterations of PRC1 genes, and the architecture, function, and activity of PRC1 complexes in cancer, have yet to be fully addressed." (PMID 30139998, 2018). "The cancer cells often exhibited cytoplasmic expression of PRC1." (PMID 28190297, 2017). "Collectively, these results suggest that silencing of PRC1 could inhibit tumorigenesis by blocking the cytokinesis in a variety of cancer cells, and further demonstrating that PRC1 is expected to become a new target for gene therapy of tumors." (PMID 28646916, 2017). "Interestingly, in agreement with PRC1 purifications from cancer cell lines, the PCGF1-containing complex associates with RYBP or YAF2 but fails to integrate chromobox domain-containing (CBX) proteins that recognize H3K27me3." (PMID 23256043, 2012). "Therefore, the effect of PRT4165 on the PRC1-repressed genes and the self-renewal capabilities of cancer stem cells would be highly relevant to its therapeutic potential." (PMID 19956605, 2009). "Indeed, our data from CRISPRi and CRISPRa cells, RITA knockout and knockdown MEFs, and various cancer cell lines suggest that RITA may modulate PRC1 distribution in mitotic spindles in metaphase cells and in the central spindle of anaphase cells." (PMID 39839673, 2024). "Indeed, of the eight CRC GWAS loci found within this subset of CRC-related smoking genes, CDCA8, CDKN3, FADS1, FADS2, MYBL2, PCSK9, and PRC1, have all been reported to be overexpressed in others cancers and to play important roles in the DNA damage response pathway." (PMID 37509213, 2023). "Hence, targeting the PRC1/2 complex might force cells to exit diapause-like quiescence in the normal, as well as the cancer, state, guiding CSCs to a proliferative stage amenable to conventional chemotherapies." (PMID 36493777, 2023). "Thus, it is of great interest to develop small molecules and PROTACS that would either specifically target a discrete PRC1 complex or at least discriminate between cPRC1 and vPRC1 complexes, particularly in the context of cancers with high levels of H2AK119ub1, like BAP1 mutant tumors." (PMID 36105358, 2022). "This may be because the auxiliary subunits of PRC1 are dynamically assembled into different PRC1 in a context-dependent manner, and thus play different or even opposite roles in the occurrence and development of cancer, but the specific mechanisms need to be further investigated clearly." (PMID 36076977, 2022). "Supporting the idea that BAP1 mutant cancers actually confers loss of PcG repression rather than the previously assumed hyperactivation of PRC1 and PRC2 activities, is the lack of response of BAP1 mutant mesothelioma patients to the EZH2 inhibitor Tazemetostat." (PMID 36105358, 2022).
cancer (continued). "To initially assess whether PRC1 components are altered in cancer, we examined the mutational frequencies of the histone H2A mono-ubiquitin ligases RNF2 (encoding RING1B) and RING1, the cPRC1 genes, and the core PRC1-encoding genes in large-scale genomic data sets from cancer patients." (PMID 30139998, 2018). "Interestingly, PRC1 is associated with a signature of 25 genes whose elevated expression is associated with chromosomal instability (CIN) and a poor prognosis in multiple cancer types." (PMID 29435157, 2018). "While PRC1 genes are not typically mutated, they are dysregulated in many cancer types." (PMID 30139998, 2018). "The polycomb gene BMI1, a component of PRC1, is overexpressed in several human cancers so that it might be expected that aberrations in this system would give rise to global alterations in gene silencing in cancer." (PMID 23086271, 2013). "Polycomb repressive complex includes PRC1 and PRC2 proteins, which play important roles in cancer development." (PMID 41154723, 2025). "Furthermore, systematic investigations of each PRC1 subcomplex (PRC1.1–1.6) under native conditions in the different cell lines may help in unlocking the complicated network of PRC1 interactors and understanding their precise role in cell biology and cancer progression in the future." (PMID 39337298, 2024). "We verified the four up-regulated lncRNAs (TCONS_00020615, TCONS_00055555, TCONS_00106091, and TCONS_00130858) and eight cancer-related mRNAs (CDCA3, DIAPH3, MCM7, NCAPG2, TPD52, PRC1, SETD6, and KIF22) involved in the ceRNA network by qRT-PCR." (PMID 37098483, 2023). "The crucial role of PRC1 and PRC2 in the fundamental cellular processes and their involvement in human pathologies such as cancer attracted intense attention over the last few decades." (PMID 36768643, 2023). "Further, while PRC1 displayed a greater module membership with the purple module, this gene was also found to be a downstream target of MYBL2 in other cancer cell lines." (PMID 37509213, 2023). "Although the zebrafish has been proven to be an excellent model for studying cancer development, the involvement of PRC1 and PRC2 in cancer biology still remains largely underexplored in zebrafish." (PMID 36768643, 2023). "By conducting a structure–activity relationship study that focused on exploring various linkers, we identified MS147, which preferentially degraded PRC1 components, BMI1 and RING1B, over PRC2 components: EED, EZH2, and SUZ12, in multiple cancer cell lines." (PMID 36737841, 2023). "It is worth noting that additional experiments are required with known PRC1‐targeting inhibitors, such as RB‐3, to further demonstrate the therapeutic potential of MS147 in PRC1‐dependent cancer." (PMID 36737841, 2023). "The results of CIBERSORT, CIBERSORT-Abs, and QUANTISEQ analyzing strategies all showed that PRC1 expression had a significant positive correlation with the infiltration of Treg cells in LIHC and other cancers including KIRC, KIRP, PCPG, and THCA." (PMID 35983074, 2022). "It is well known that PRC1 and PRC2 complexes regulate stem cell pluripotency, cell fate decisions, and development and are dysregulated in many cancer types, facilitating cancer stem cell maintenance." (PMID 36361869, 2022). "Accumulating evidence suggests that the PRC1 complex member CBX2 is overexpressed in solid tumors and promotes cancer cell survival." (PMID 35681235, 2022). "The Genomics of Drug Sensitivity in Cancer (GDSC) database and the Cancer Therapeutics Response Portal (CTRP) were used to evaluate the sensitivity and resistance of SLK, MRPL51, and PRC1-targeting drugs." (PMID 35982906, 2022). "However, the precise roles of the various subunits of PRC1 in cancer remain to be defined, and future work should further delineate the molecular implications of these components in depth and identify appropriate therapeutic approaches to rescue their dysregulation in different cancers." (PMID 36076977, 2022).
cancer (continued). "TIDE analysis demonstrated the correlation between PRC1 expression and MDSC infiltration in pan-cancer fields, especially in LIHC." (PMID 35983074, 2022). "Beyond EZH2, overexpression of another Polycomb protein in PRC1, chromobox homolog protein 2 (CBX2), is also associated with poor survival by maintaining CSCs, which might be an emerging approach targeting Polycomb proteins that could be used in cancer therapy." (PMID 35509102, 2022). "Polycomb Group (PcG) proteins including Polycomb Repressive Complexes, PRC1 and PRC2 are widely recognized to mediate gene silencing of developmental genes and also play a role in repressing genes in cancer." (PMID 33924927, 2021). "Our findings support a model by which upregulation of USP7 in cancers resulted in an elevated abundance of EZH2, as well as H2BK120ub1 removal and an increased level of H3K27me3, which is independent on the PRC1 complex." (PMID 33849069, 2021). "The polycomb group (PcG) proteins constitute PRC1 and PRC2 complex that function as epigenetic regulators of gene expression in cell fate, development, and cancer." (PMID 33779563, 2021). "Specifically, during the course of D. melanogaster development and larval imaginal disc differentiation, PRC1 and PRC2 can be functionally uncoupled and PRC1 redeployed to new target genes that are enriched for cancer-related ontologies." (PMID 33126754, 2020). "In cancer cells, PRC2 sustains levels of PRC1 complexes by preventing the upregulation of microRNAs (miRNAs) that downregulate PRC1 subunits." (PMID 34968234, 2019). "Our finding that PRC1 is a substrate of CDK16 is of particular interest, considering the roles of these two proteins in cancer cell proliferation." (PMID 30992425, 2019). "Interestingly, experiments using different cancer cell lines showed that the effect of PRC1 downregulation on cell proliferation varied significantly depending on the cell line, suggesting that the relevance of PRC1 to cell proliferation may be context-dependent." (PMID 30992425, 2019). "However, whether PRC1 affects cancer development through its role in mitosis is unclear." (PMID 29748662, 2018). "BMI1 is a core component of the polycomb repressive complex 1 (PRC1) and emerging data support a role of BMI1 in cancer." (PMID 27827373, 2016). "PANDAR interacts with polycomb repressive complexes (PRC1 and PRC2) and the transcription factor NF-YA to repress the transcription of senescence-promoting genes in cancer cells." (PMID 27206339, 2016). "Consistent with its interaction with PRC1 and binding to chromatin, SCML2 has profound impact on the cellular activity when ectopically expressed in transformed or cancer cells." (PMID 25634095, 2015). "Polycomb repressive complexes (PRC1 and PRC2) are epigenetic regulators that act in coordination to influence multiple cellular processes including pluripotency, differentiation, cancer and senescence." (PMID 26416703, 2015). "Strikingly, there is evidence thatANLN, ECT2, PRC1,RACGAP1, ASPM, and PLK1 areupregulated in a variety of human cancers and that their overexpression oftencorrelates with poor outcome (see for example and references therein)." (PMID 21386884, 2011). "For instance, PcG proteins suppress expression of Homeobox genes and the p16-Arf-p15 locus mainly through the Polycomb repressive complex-1 and -2 (PRC1 and PRC2), which control cell fate and cancer development." (PMID 21060834, 2010). "Additionally, the roles of PRC1 subunits and EZH1 proteins in inflammation and cancer are not fully understood." (PMID 40042761, 2025). "The disruption of PRC1 function results in impairments in cell movement, which in turn facilitates CIN, ultimately contributing to tumour heterogeneity and the progression of cancer." (PMID 40845073, 2025). "IHC images from the HPA indicated that PRC1 protein expression was higher in PDAC than in pancreases without cancer." (PMID 39409930, 2024).
cancer (continued). "PRC1 expression was notably higher in patients with nodal metastasis at stage N1 compared to the cohort without cancer." (PMID 39409930, 2024). "The BMI1 gene (the protein product of which is a part of the PRC1 complex) was also hypomethylated in many regions not only in hgOvCa (exons, 3′UTR and distal promoter) but in both carcinoma groups (proximal promoter and the first exon), which implies its high expression in OvCa (GR file)." (PMID 39456618, 2024). "Furthermore, positive correlations of PRC1 and some immune checkpoint genes (CD274, CTLA4, HAVCR2, LAG3, PDCD1, PDCD1LG2, TIGIT, and CD86) were observed in several cancers, especially BLCA, BRCA, KIRC, LUAD, LIHC, PRAD and THCA." (PMID 37563591, 2023). "Here, we unveil that, in 28 cancer types, PRC1 is higher expressed in tumor tissues than in non-malignant tissues." (PMID 37563591, 2023). "To clarify the mechanism synergistic anti-cancer effect of FYLM, we investigated the protein expression of PRC1, Wnt pathway-related protein (β-catenin, c-Myc, c-Jun) and EGFR pathway-related protein (p-EGFR, EGFR, p-Akt and Akt) in xenograft tumor tissues by western blot and immunohistochemistry." (PMID 36744262, 2023). "Regarding the top genes present in these terms, we found genes involved in carcinogenesis with potential prognostic and therapeutic roles in cancer (FBXO5 and SMC4) and also PRC1, whose deregulation is related to chromosomal instability and tumor heterogeneity." (PMID 35954157, 2022). "Collectively, these data support that CDK16 inhibition is involved in multiple cancer-related signaling pathways, which may contribute to the function of CDK16 in regulating TNBC progression together with PRC1." (PMID 35449080, 2022). "And histone H2A ubiquitination induced by PRC1 could repress SLC7A11 expression and then regulate ferroptosis of cancer cells." (PMID 35197055, 2022). "In addition, the misregulation of Polycomb repressive complexes, PRC1 and PRC2, which is common in many cancers, affects pericentromeric silencing." (PMID 35885937, 2022). "It is important to point out although PRC1 is a potential therapeutic target for multiple cancer types, there are no known specific inhibitors directly targeting PRC1." (PMID 35449080, 2022). "Studies have pointed out that the dysregulation of the protein regulator 1 (PRC1) of cytokinesis led to cytokinesis defects in the cell cycle, which in turn promoted chromosomal instability (CIN), thereby promoting tumor heterogeneity and cancer progression." (PMID 36462500, 2022). "It has been suggested that overexpression of PRC1 triggers the onset of various cancers yet its potential roles in LUAD have not been fully understood." (PMID 36324565, 2022). "Polycomb repressive complex-1 (PRC1) induces transcriptional repression by regulating monoubiquitination of lysine 119 of histone H2A (H2AK119) and as such is involved in a number of biological and pathological processes including cancer development." (PMID 33779563, 2021). "To do so, we initially employed PTC‐209, an inhibitor that reduces BMI1 protein levels and lowers PRC1 activity in cancer cells, with minimal effects in noncancerous cell line models." (PMID 33523558, 2021). "In this study, ChIP-seq was performed on an LCL for BMI1 and SUZ12, subunits of PRC1 and PRC2, respectively—two protein complexes shown to be critically important in the regulation of genes involved in differentiation, proliferation and cancer development." (PMID 30649516, 2019). "The data suggest that PRC1 is overexpressed in human NSCLC, implying that PRC1 may have a part in cancer progression." (PMID 28646916, 2017). "Chromatin repressive complexes like the PcG protein complexes PRC1 and PRC2 are essential mediators of stemness and critical contributors to cancer pathogenesis by suppressing the expression of tumor-suppressor genes and developmental regulators in a context-dependent, cell-type-specific manner." (PMID 27317769, 2016).
cancer (continued). "We used an approach for dynamic proteomics to measure the protein levels of PRC1 (protein regulator of cytokinesis 1, NM_003981), ANLN (anillin, NM_018685) and YB1 (Y-box binding protein-1, NM_004559) in individual living human cancer cells over several cell cycles." (PMID 19381343, 2009). "Several studies have reported that BMI-1 has been shown to regulate DNA end resection and homologous recombination repair, whereas other studies have suggested that another PRC1 subunit, RYBP, could inhibit homologous recombination and sensitize cancer cells to poly ADP-ribose polymerase inhibitors." (PMID 39793896, 2025). "Whether other steroid hormones, such androgens and progesterone, regulate PRC1 recruitment to activate oncogenic pathways in other cancer types is not known." (PMID 36105358, 2022). "Polycomb repressive complex 1 (PRC1), composed of four subunits PHC, BMI-1, CBX, and Ring 1A/B, is an E3 ubiquitin ligase that monoubiquitinates histone H2A lysine 119 (H2AK119ub1), which silences target gene expression and promotes dedifferentiation and stemness during development and cancer." (PMID 35892678, 2022). "RING1B is the more commonly upregulated RING paralog in cancer, and as the catalytic subunit of PRC1, represents a good therapeutic target; in contrast, RING1A is commonly downregulated in cancers and low expression correlates with poor prognosis, indicating that it may act as a tumor suppressor." (PMID 34617019, 2021). "The finding that transient PRC1 depletion leads to epigenetic tumors without inducing genome instability, while prolonged inactivation of this complex results in DNA repair defects and massive genome rearrangements, is also important to inform cancer treatment approaches." (PMID 38888809, 2024). "Therefore, it is likely that PRC1 gene knockdown could contribute to cancer repression via mechanisms independent of its cytokinesis‐related function." (PMID 28190297, 2017). "The recruitment of HDAC3, as well as the suppression of cancer metastasis by CBX4, are neither dependent on its chromodomain nor its PRC1 complex." (PMID 32111827, 2020). "In cultured immortal or cancer cells, human SCML2A interacts with PRC1 and binds to non-coding RNAs, whereas human SCML2B regulates the cell cycle by binding to CDK2." (PMID 25634095, 2015). "HOTAIRM1 was previously shown to interact with polycomb repressive complexes 1 (PRC1) and 2 (PRC2), but was not reported to be involved in cancer." (PMID 25296969, 2014). "Furthermore, high PRC1 expression had a negative correlation with CD4+ T cells, which are crucial for the immune response against cancers." (PMID 39409930, 2024).